POU2F1 (POU class 2 homeobox 1)
Diseases named in the same sentence as POU2F1 in open-access papers (continued):
Sharing a sentence is not in itself a finding about the gene and the disease.
colon carcinoma (continued). "Our findings suggest that the POU2F1-ALDOA axis may be new therapeutic targets to overcome oxaliplatin resistance in colon cancer." (PMID 34997215, 2022). "Next, we tested the hypothesis that POU2F1 could directly induce ALDOA expression in colon cancer cells." (PMID 34997215, 2022). "Hence, the POU2F1-ALDOA axis enhanced the oxaliplatin resistance in colon cancer cells by increasing glycolysis and PPP activity." (PMID 34997215, 2022). "However, it is still unclear how POU2F1 regulates glycolysis and promotes the progression of colon cancer." (PMID 34997215, 2022). "Furthermore, POU2F1 enhanced the survival, proliferation, and clonogenicity of colon cancer cells by up-regulating ALDOA expression to enhance the glycolysis and PPP activity, and attenuating the DNA damage-induced apoptosis." (PMID 34997215, 2022). "We hypothesized that POU2F1 could modulate the sensitivity of colon cancer cells to oxaliplatin and 5-Fu." (PMID 34997215, 2022). "POU2F1 over-expression significantly promoted cell proliferation, colony formation and implanted tumor growth, while POU2F1 silencing had remarkably opposite effects on colon cancer cells (p < 0.05)." (PMID 34997215, 2022). "Together, these results indicated that up-regulated POU2F1 expression was associated with worse prognosis of colon cancer, suggesting that POU2F1 may act as an oncogenic factor of colon cancer." (PMID 34997215, 2022). "Our data support the notion that POU2F1 acts as an oncogenic factor to promote the progression of colon cancer and may be a valuable therapeutic target for colon cancer." (PMID 34997215, 2022). "Thus, POU2F1 supported the oxaliplatin resistance in colon cancer cells, dependent on up-regulating ALDOA expression." (PMID 34997215, 2022). "Moreover, we explored the role of the POU2F1-ALDOA axis in oxaliplatin resistance of colon cancer cells." (PMID 34997215, 2022). "Hence, the POU2F1-ALDOA axis supported the oxaliplatin resistance of colon cancer cells by enhancing the glycolysis and PPP activity in vivo and in vitro." (PMID 34997215, 2022). "To further analyze the role of the POU2F1-ALDOA axis in oxaliplatin resistance of colon cancer cells in vivo, we established xenograft colon tumors by subcutaneously implanting with HCT116/L cells, HCT116/L-sh-POU2F1 cells, and HCT116/L-sh-POU2F1 + ALDOA cells into BALB/c nude mice." (PMID 34997215, 2022). "Conceivably, the POU2F1-ALODA axis may be promising targets for overcoming oxaliplatin resistance in treatment of colon cancer." (PMID 34997215, 2022). "Additionally, the GSEA analysis of GSE121842 displayed that gene sets related to glycolysis and PPP were enriched in the high-POU2F1 expressing colon cancer cases." (PMID 34997215, 2022). "Moreover, activation of the POU2F1-ALDOA axis decreased the sensitivity to oxaliplatin in colon cancer cells." (PMID 34997215, 2022). "Interestingly, we found that POU2F1 and ALDOA expression were paralleled in colon cancer tissues and cell lines; altered POU2F1 expression modulated ALDOA expression in colon cancer cells; both POU2F1 and ALDOA expression appeared to a better biomarker for prognosis of colon cancer." (PMID 34997215, 2022). "Moreover, high levels of POU2F1 expression were detected in colon cancer tissues." (PMID 34997215, 2022). "Our data indicated that POU2F1 directly bound to the ALDOA promoter and enhanced its activity in colon cancer cells." (PMID 34997215, 2022). "Compared with the controls, POU2F1 over-expression decreased NADP+/NADPH ratios and intracellular ROS levels while POU2F1 silencing increased them in colon cancer cells (p < 0.05)." (PMID 34997215, 2022). "POU2F1 enhanced the proliferation, aerobic glycolysis and the pentose phosphate pathway (PPP) activity, but reduced oxidative stress and apoptosis in colon cancer cells, dependent on up-regulating ALDOA expression." (PMID 34997215, 2022).
colon carcinoma (continued). "The impacts of POU2F1 on aldolase A (ALDOA) expression and malignant behaviors of colon cancer cells were examined." (PMID 34997215, 2022). "The POU2F1-ALDOA axis was crucial for the metabolic reprogramming, glycolysis, growth and chemoresistance of colon cancer." (PMID 34997215, 2022). "In our study, we found that POU2F1 over-expression enhanced glycolysis and PPP activity while POU2F1 silencing had opposite effects on colon cancer cells." (PMID 34997215, 2022). "We further tested the function of ALDOA in the POU2F1-enhanced glycolysis and PPP activity in colon cancer cells." (PMID 34997215, 2022). "The POU2F1-ALDOA axis attenuated intracellular ROS production and subsequent DNA damages and apoptosis, leading to the oxaliplatin resistance in colon cancer cells." (PMID 34997215, 2022). "The formed POU2F1-ALDOA axis promoted malignant behaviors and oxaliplatin resistance in colon cancer by enhancing glycolysis and PPP activity and protecting from oxidative stress-induced DNA damages and apoptosis." (PMID 34997215, 2022). "Together, these data indicate that POU2F1 promotes the malignant behaviors of colon cancer by up-regulating the ALDOA expression, and the POU2F1 and ALDOA forms the axis to enhance the progression of colon cancer." (PMID 34997215, 2022). "We found that POU2F1 over-expression significantly decreased the sensitivity to oxaliplatin, but not to 5-Fu, in colon cancer cells (p < 0.05)." (PMID 34997215, 2022). "Such novel findings may provide new insights into the molecular mechanisms by which the POU2F1-ALDOA axis promotes malignant behaviors and oxaliplatin resistance of colon cancer." (PMID 34997215, 2022). "POU2F1 over-expression significantly increased glucose consumption, lactate production levels and glucose-6-phosphate-dehydrogenase (G6PD) activity, whereas POU2F1 silencing had opposite effects on colon cancer cells (p < 0.01)." (PMID 34997215, 2022). "It suggests that POU2F1 may increase glycolysis and PPP activity to enhance the malignant behaviors of colon cancer cells." (PMID 34997215, 2022). "High-POU2F1 expression was also obviously detected in colon cancer cell lines compared to human non-tumor colonic epithelial HCoEpiC cells (p < 0.05)." (PMID 34997215, 2022). "It is notable that an alternation in the expression of POU2F1 or ALDOA did not significantly change the sensitivity to 5-FU in colon cancer cells." (PMID 34997215, 2022). "We further texted whether the change in POU2F1 expression could modulate the H2O2-induced γ-H2AX and PCNA expression in colon cancer cells." (PMID 34997215, 2022). "The paralleled expression of POU2F1 and ALDOA suggests that POU2F1 may induce ALDOA expression to regulate the glycolysis and PPP activity in colon cancer." (PMID 34997215, 2022). "Next, we tested whether the POU2F1-ALDOA axis could modulate the glycolysis and PPP activity in oxaliplatin-resistant colon cancer." (PMID 34997215, 2022). "Therefore, both POU2F1 and ALDOA expression levels may be valuable biomarkers for the prognosis of colon cancer." (PMID 34997215, 2022). "We found that POU2F1 transcripts were positively correlated with hexokinase 2 (HK2), 6-phosphofructo-2-kinase/fructose-2,6-biphosphatase 2 (PFKFB2), ALDOA, pyruvate kinase M1/2 (PKM), lactate dehydrogenase A (LDHA), G6PD, and ribose 5-phosphate isomerase A (RPIA) levels in the colon cancer tissues." (PMID 34997215, 2022). "Hence, targeting POU2F1 and/or ALDOA may be a promising strategy to overcome oxaliplatin resistance in colon cancer." (PMID 34997215, 2022). "In addition, higher POU2F1 expression was significantly associated with higher TNM stage (p = 0.002) and metastases (p = 0.013), but not with age, gender and the differentiation status in 184 colon cancer patients." (PMID 34997215, 2022).
diabetes (2 papers, 2015 to 2018). "Consistent with diabetes traits, the POU2F1 gene set (PID:1551) is insignificant (p-value > 0.05), while all other six gene sets have p-value < 0.05 in meta-analysis of binomial test." (PMID 29503662, 2018). "Except for POU2F1 (PID:1551), all other six gene sets had strong significant associations with diabetes traits after Bonferroni correction (p-value < 0.007)." (PMID 29503662, 2018). "Therefore, the component gene of NPAS3 and TFs of FOXO4 and POU2F1 can form another hypothesis of potential genetic pathways related to diabetes pathogenesis." (PMID 25898945, 2015).
lung carcinoma (2 papers, 2020 to 2021). "Next we should detect whether POU2F2 and POU2F1 have synergistic effect in the progress of lung cancer." (PMID 33832481, 2021). "Our data confirmed that POU2F1 transcriptionally activated AGO1 and therefore promoted the progression of lung cancer, and the precise molecular mechanisms and the signaling pathways need further study." (PMID 33832481, 2021). "In addition, POU2F1 showed the highest expression levels in the lungs, which may be related to the expression and important roles of SLC7A11 in response to lung cancer." (PMID 32443864, 2020).
prostate carcinoma (2 papers, 2021). A carcinoma that arises from epithelial cells of the prostate gland. "In prostate cancer, POU2F1 is a co-regulator of AR, leading to AR hypersensitivity and driving androgen-independent cancer progression." (PMID 33541355, 2021).
psoriasis (2 papers, 2020 to 2024). An autoimmune condition characterized by red, well-delineated plaques with silvery scales that are usually on the extensor surfaces and scalp. "Of the 10 most significantly enriched upstream regulators in each comparison, Sterol Regulatory Element Binding Transcription Factor 1 (SREBF1) was predicted to be enriched only in psoriasis lesions, and POU class 2 homeobox 1 (POU2F1) only in PsA lesions." (PMID 37137278, 2024). "rs643177 is a fine-mapped psoriasis SNP1 and has evidence of allele-specific binding of the TF Pou2f1." (PMID 32144282, 2020).
Sepsis (2 papers, 2021 to 2022). Sepsis is defined as life-threatening organ dysfunction caused by a dysregulated host response to infection. "Further rescue experiment indicated that knockdown of POU2F reversed the positive impact of miR-31-5p silencing on sepsis progression, suggesting the involvement of POU2F1 in sepsis-induced inflammatory response." (PMID 33710444, 2021). "In summary, all these findings demonstrated that NEAT1 promoted inflammatory response in sepsis via the miR-31-5p/POU2F1 axis, and it provided a novel therapeutic target for sepsis." (PMID 33710444, 2021). "To probe the underlying molecule mechanism of miR-31-5p on sepsis progression, we used miRwalk, ENCORI, and TargetScan prediction software to predict the target gen of miR-31-5p determined POU2F1 since it exerts major roles in sepsis progression." (PMID 33710444, 2021). "We further explored the downstream cascade of NEAT1/miR-31-5p axis involved in sepsis-induced inflammatory response, and found miR-31-5p target gene, POU2F1." (PMID 33710444, 2021). "In a word, this study indicates that NEAT1 inhibits the LPS-induced progression of sepsis in RAW264.7 cells by modulating miR-31-5p/POU2F1 axis, suggesting that NEAT1 will be the potential therapeutic target for sepsis." (PMID 33710444, 2021). "In this study, our data demonstrated that NEAT1 aggravated LPS-induced inflammatory responses and cell apoptotic activity by targeting miR-31-5p and POU2F1, uncovering the potential therapeutic role of NEAT1 in sepsis-induced inflammatory response." (PMID 33710444, 2021). "Finally, to ascertain NEAT1 promoted sepsis progression by miR-31-5p/POU2F1 axis, we co-transfected RAW264.7 cells with sh-NEAT1 (or sh-NC), sh-POU2F1, and miR-34b-5p inhibitor before LPS stimulation." (PMID 33710444, 2021).
Autoimmunity (1 paper, 2019). The occurrence of an immune reaction against the organism's own cells or tissues. "We used a conditional mouse Oct1 (Pou2f1) allele and a CD4-Cre driver to determine the effect of T cell-specific Oct1 loss on autoimmune- and viral-induced neuroinflammation using an autoantigen-driven EAE model of autoimmunity and a JHMV model of viral infection." (PMID 31266507, 2019).
colitis (1 paper, 2024). Inflammation of the colon. "In contrast, the deletion of POU2F1 transcription factor revealed an improvement in cell homeostasis but blocked the recovery of the tissue in a colitis model." (PMID 38891888, 2024). "Therefore, among all the molecular targets of our miRNA candidates, POU2F1, SOCS1, and circ-SHPRH are better characterized for their involvement in colitis-associated CRC." (PMID 38891888, 2024).
colon adenocarcinoma (1 paper, 2024). "Evidently, the levels of POU2F1 expression were negatively correlated with TRIM2F1 expression in 458 colon adenocarcinoma cases in The Cancer Genome Atlas (TCGA) database (r=-0.1568, P<0.001)." (PMID 38385081, 2024).
glioblastoma (1 paper, 2016). The most malignant astrocytic tumor (WHO grade IV). "The second promoter region was linked with 6 of the GBM48 panel’s genes which contained the CWNAWTKWSATRYN motif for the POU2F1 transcription factor (also known as Oct-1, FDR-adjusted p-value of 4.73 x 10^-4), which has been shown to be differentially expressed in human glioblastoma cells." (PMID 27855170, 2016).
glioma (1 paper, 2023). A benign or malignant brain and spinal cord tumor that arises from glial cells (astrocytes, oligodendrocytes, ependymal cells). "We further explored the relationship between the expression of POU2F1 and RAD51B in lymphoblastic cells and glioma tissues." (PMID 37858068, 2023). "Consistently, positive correlation between the expression of POU2F1 and RAD51B was found in lymphoblastic cells and glioma tissues." (PMID 37858068, 2023).
leukemia (1 paper, 2024). A malignant (clonal) hematologic disorder, involving hematopoietic stem cells and characterized by the presence of primitive or atypical myeloid or lymphoid cells in the bone marrow and the blood. "POU2F1 interacts closely with c-Myc to regulate cell cycle progression, and prior reports have shown that inhibition of Myc pathways can prevent GVHD while preserving graft-versus-leukemia." (PMID 39028952, 2024).
tumor (26 papers, 2014 to 2026). "As indicated by PCR assay, POU2F1 overexpression was associated with increased LINC01564 in GC tumor." (PMID 35562740, 2022). "Tumor-infiltrating CD4+ T cells (C12_CD4) were associated with binding motif enrichment for cluster-specific TFs such as members of the POU domain family (POU2F1, POU2F2 and POU2F3), in addition to TF programs shared with dysfunctional CD8+ T cells." (PMID 35668194, 2022). "Overall, mutated-β-catenin represses IRF2, POU2F1, and likely other TFs, which limits transcription of key signaling molecules (i.e., cytokines and chemokines) important for priming lymphocyte recruitment needed for effective anti-tumor immunity." (PMID 40442146, 2025). "Overall, mutated-β-catenin represses IRF2, POU2F1, and likely other TFs, which limits transcription of key chemokines and cytokines important for priming recruitment of lymphocytes needed for an effective anti-tumor immunity and ICI response." (PMID 39711542, 2024). "In addition, POU2F1 is implicated in immunity and inflammation, activity maintenance of tumor stem cells as well as tumorigenesis, and development through modulation of the expression of the tissue-specific target gene." (PMID 34257651, 2021). "Our research reveals a key player in this challenge-POU2F1, a transcription factor known to drive tumor progression." (PMID 41793212, 2026). "We also observed a significant decrease in overall gross tumor burden at 10.7-weeks post-HDTVi in POU2F1-overexpression β-N model and via histology." (PMID 40442146, 2025). "POU2F1 is a transcriptional activator that is highly expressed in a variety of cancers and promotes tumor development." (PMID 40781327, 2025). "We also observed here a significant decrease in overall gross tumor burden at 10.7-weeks post-HDTVi in Pou2f1-overexpression β-N model and via histology." (PMID 39711542, 2024). "POU2F1, a multifunctional transcription factor, promotes tumorigenesis and progression by regulating tumor-specific gene expression." (PMID 37370118, 2023). "Our findings suggest that in OC, POU2F1 promotes tumour cell proliferation, EMT migration, and invasion." (PMID 37845675, 2023). "POU2F1 promotes GC cell viability and tumor growth via transcriptional activation of lncRNA TTC3-AS1, demonstrating that POU2F1 is highly expressed in GC patients and predicts poor prognosis." (PMID 37370118, 2023). "The expression of EMT genes aids in the migration of EMT in ovarian cells and initiates proliferation and immune regulation when POU2F1 is upregulated, which triggers tumour promoter factors that impair the immune system's health." (PMID 37845675, 2023). "HE staining showed that the tumors formed in the POU2F1 (OE) group were substantially larger than those in the control group, while LINC01564 knockdown suppressed the growth of tumor with POU2F1 (OE)." (PMID 35562740, 2022). "In vivo assays showed that tumor with higher expression of POU2F1 had stronger staining of ki67 and produced more MMP9." (PMID 35562740, 2022). "we observed that POU2F1 silencing significantly enhanced the sensitivity of HCT116/L tumors to oxaliplatin by decreasing tumor sizes and weights (p < 0.05, p < 0.01), compared to HCT116/L tumors." (PMID 34997215, 2022). "POU2F1 was shown to regulate regeneration and tumor transformation in the HCT116 cell line (rectal tumor cells) and in other tumors." (PMID 35538289, 2022). "Evidently, POU2F1 is up-regulated in human gastric, intestinal and colon stem cells and positively correlated with tumor aggressiveness." (PMID 34997215, 2022). "LINC01564 knockdown not only decreased LINC01564 expression, but also inhibited POU2F1 expression in GC tumor induced by POU2F1 overexpression vector." (PMID 35562740, 2022). "POU2F1 knockdown resulted in a significant decrease in proliferation and growth in cell lines of these tumor types." (PMID 35538289, 2022).